BRCA2 (BRCA2 DNA repair associated)
Diseases named in the same sentence as BRCA2 in open-access papers (continued):
Sharing a sentence is not in itself a finding about the gene and the disease.
tumor (continued). "FoundationONE CDx (version T7) testing identified a deleterious BRCA2 c.5727_5728insG (N1910fs*2) mutation in the original tumor biopsy." (PMID 32171277, 2020). "One HRD tumor carried a pathogenic variant in BRCA2 with LOH of the wild-type allele (case 43), while BRCA1 promoter hypermethylation was observed in another HRD tumor (case 49)." (PMID 33003546, 2020). "A BRCA mutation is a mutation in either the BRCA1 or BRCA2 gene, both of which are tumor-suppressor genes." (PMID 33019612, 2020). "It has been shown previously that germline BRCA1/BRCA2 mutations leave a recognizable imprint on a tumor’s mutational landscape." (PMID 32997669, 2020). "The lack of synergy observed in the parental model further reflects the specificity of the combination therapy to the BRCA2-deficient model, introducing a second layer of tumor targeting in addition to HER2 targeting." (PMID 31618864, 2019). "The majority of these off-label indications were BRCA1 or BRCA2 mutations (90/111; 81%), which were documented across 20 different tumor types." (PMID 30658646, 2019). "We found broadly consistent associations of height in both BRCA1 and BRCA2 mutation carriers by menopausal status and by tumour histological type and grade." (PMID 31213659, 2019). "The two tumours with primary resistance to olaparib and one tumour exhibiting a partial response were found to harbour secondary mutations of BRCA2 that restored the ORF of the gene." (PMID 30672100, 2019). "In conclusion, this research combines both pedigree and tumor data to identify the main variables associated with the presence of a BRCA1 or BRCA2 germline mutation." (PMID 31244284, 2019). "Mutations in the BRCA1 and BRCA2 genes are perhaps the most well-known causes of hereditary BC due to their disruption of the genes' tumor-suppressing functions." (PMID 31528229, 2019). "Unfortunately, samples were not available for segregation studies of these missense variants in affected relatives and to assess for somatic inactivation of the second BRCA2 allele in the corresponding tumours." (PMID 31469826, 2019). "Among the 221 cases successfully analyzed, 62 (28.1%) cases harbored tumor BRCA1 or BRCA2 pathogenic/likely pathogenic mutations." (PMID 31653094, 2019). "We further reduced the dose administered in mice and observed that BRCA2‐deficient tumours were also eliminated even at doses of 1 mg/kg daily chlorambucil." (PMID 31273933, 2019). "The tumor suppressor BRCA2 participates in multiple pathways during both meiosis and mitosis that are critical for maintaining genomic integrity, and loss of BRCA2 function can lead to both structural aberrations and aneuploidy." (PMID 30930946, 2019). "Pathological characteristics of BC in BRCA2 mutation carriers are less indicative (higher tumor grade, frequent ER-positivity, and HER-2 negativity), resembling sporadic tumors." (PMID 31141992, 2019). "BRCA2 mutations have been found to be associated with an increased mutational load, neoepitope formation, increased tumor-infiltrating lymphocytes, and a favorable response to immune checkpoint blockade." (PMID 31549213, 2019). "Combined, our results describe a mechanism by which autocrine TNFα signaling, induced by cGAS/STING signaling upon loss of the BRCA2 tumor-suppressor gene, limits tumor cell viability." (PMID 30626869, 2019). "These and other findings have suggested that breast tumorsarising in BRCA1 mutation carriers are associated with moreaggressive tumor characteristics compared to BRCA2 mutationcarriers." (PMID 31067289, 2019). "Palb2-, Brca1- or Brca2- deficient tumor cells in comparison to KPC or Palb2flox/+-KPC tumor cells are exquisitely sensitive to DNA damage inducing agents, including Olaparib, MMC and Cisplatin." (PMID 31877165, 2019). "While these factors are biochemically distinct, they are both synthetic lethal with loss of the BRCA1 and BRCA2 tumor suppressor genes, and hence are emerging therapeutic targets." (PMID 31381562, 2019).
tumor (continued). "We examined heterogeneity of these associations with respect to the mutation carried (BRCA1 vs BRCA2), menopausal status, tumour histology, and tumour grade." (PMID 31213659, 2019). "Of note, there was a trend towards a lower intratumoral CD8+ to FOXP3+ ratio in BRCA2-mutated tumors that needs to be carefully interpreted, but suggests a more suppressed tumor immune microenvironment." (PMID 31549213, 2019). "As the causative mutations are distributed throughout the genes, we here recommend that that the technique is suitable to detect variants in BRCA1 and BRCA2 and other tumor suppressor genes." (PMID 31131559, 2019). "Due to compromised homologous recombination (HR) repair, BRCA1‐ and BRCA2‐mutated tumours accumulate DNA damage and genomic rearrangements conducive of tumour progression." (PMID 31273933, 2019). "The tumour phenotypes associated with PALB2 tumours are very similar to those associated with BRCA2 tumours, with 61% of invasive tumours having associated DCIS." (PMID 31060593, 2019). "For BC, BRCA carriers showed a more advanced histological stage, higher risk of bilateral neoplasms (OR = 4.3; 95% CI = 1.3–11.4, for BRCA2 carriers) and worse OS rate at 5-, 10- and 15- years, than women with sporadic tumors." (PMID 31771539, 2019). "PARP inhibition causes synthetic lethality in combination with severe HR deficiency such as of tumor cells from BRCA1 or BRCA2 mutation carriers upon inactivation of the wild‐type allele." (PMID 31347298, 2019). "The inactivation of BRCA1 or BRCA2 due to somatic mutations or BRCA1 promoter methylation is also observed in these tumor types." (PMID 31727117, 2019). "Genetic testing detected a pathogenic nonsense germline mutation in BRCA2 c.9310A>T (p.K3104X), which was identical to the variant detected in tumor." (PMID 31608315, 2018). "Genetic testing detected a pathogenic frameshift germline mutation in BRCA2 c.89insA (p.L29fs), which was identical to the variant detected in tumor." (PMID 31608315, 2018). "These provided a quantification of exome-seq measurement uncertainty, e.g. a variant in BRCA2 in the TM00099 tumor yielded AFs of 0.545 ± 0.015 across 6 samples, compared to the AF = 0.5 heterozygous expectation." (PMID 30560892, 2018). "ATM-associated tumours also differ from luminal BRCA2-associated tumours, which can also display the HRD signature." (PMID 29665859, 2018). "Genetic testing detected double pathogenic nonsense germline mutations in BRCA1 c.188T>A (p.L63X) and in BRCA2 c.6922A>T (p.K2308X), which were identical to the variants detected in tumor." (PMID 31608315, 2018). "BRCA2 expression was significantly associated with sex of patients (P = 0.007), higher tumor stage (P = 0.002), distant metastasis at diagnosis (P = 0.008), and higher histologic grade (P = 0.003)." (PMID 29784019, 2018). "Pathogenic homozygous BRCA1 and BRCA2 mutations were later detected in tumor cells by next-generation sequencing." (PMID 29729664, 2018). "For BRCA2 mutated pancreatic cancer there is in vitro and in vivo data suggesting a higher sensitivity of tumor cells to DNA-crosslinking agents." (PMID 30541485, 2018). "We found that tumor intrinsic molecular differences such as BRCA1/BRCA2 mutation and ER signaling were mainly associated with patient age and menopausal status." (PMID 29713003, 2018). "BRCA2 germline mutations in men with PC have been associated with an aggressive tumor phenotype, a more advanced tumor stage at the diagnosis and poor survival outcomes at any disease stage, including the localized/locally advanced disease." (PMID 30234108, 2018).
tumor (continued). "BRCA1 and BRCA2 are well-characterised tumour suppressor genes that when heterozygously mutated in the germ line, increase the risk substantially for several malignancies, including breast, ovarian, pancreatic and prostate cancer." (PMID 30428574, 2018). "Recently, it has been reported that BRCA2-associated MBCs are characterized by elevated tumor methylation." (PMID 29731982, 2018). "BRCA2 encodes for a known tumor suppressor that is involved in the repair of double-strand breaks in DNA by homologous recombination." (PMID 29522538, 2018). "The susceptibility to CM and UM associated with BRCA1/BRCA2 is an example of melanotic tumours being part of a spectrum of tumours associated with well characterised cancer predisposition syndromes." (PMID 29641532, 2018). "In arm A, 57% and 43% of patients carried deleterious BRCA1 and BRCA2 mutations, respectively; 56% and 44% had triple-negative and HR+ disease; and 59% had more than two tumor sites (liver metastasis, 52%; CNS metastasis, 6%)." (PMID 30240327, 2018). "One tumor from a ST patient had a somatic missense mutation in BRCA2 (p.Pro2257Ser, MAF = 0.15) that is classified as tolerated and benign by SIFT (score = 0.12) and PolyPhen2 (score = 0.047), and therefore considered as non-pathogenic." (PMID 30382883, 2018). "Tumour growth of the BRCA2 deficient tumours remained suppressed for 10–20 days after ceasing oral dosing with CX-5461 (vertical dashed lines)." (PMID 28211448, 2017). "Our in vitro data also corroborate that evofosfamide in combination with IR is more potent in BRCA2-deficient tumor cells than in their BRCA2-wildtype counterpart cells." (PMID 28423594, 2017). "As a result, the liver metastasis contained one BRCA2 allele that was wildtype, rendering the metastasis BRCA2-proficient, which was in keeping with the tumor growth observed despite ongoing PARP inhibitor treatment." (PMID 29262651, 2017). "In general, tumours from patients with a germline BRCA2 mutation contain an inactivating mutation of the second allele." (PMID 29184099, 2017). "PALB2 is a DNA maintenance gene, where the encoded protein binds to and colocalizes with BRCA2 in nuclear foci, and plays a role of tumor suppression." (PMID 29212173, 2017). "Two cases of STICs and one case of occult carcinoma were found only within fallopian tubes, consistent with the fallopian tube being the origin for BRCA1 and BRCA2 mutation-associated tumours." (PMID 28285341, 2017). "Paradoxically, while loss of BRCA2 promotes tumor formation, it also causes cell lethality, although how lethality is triggered is unclear." (PMID 28904335, 2017). "Strikingly, CX-5461 treatment substantially and significantly inhibited the growth rate of tumours formed from two BRCA2 deficient HCT116 cell lines (B18 and B46), in a dose-dependent manner." (PMID 28211448, 2017). "The same mechanism has been shown in human tumor cell lines harboring BRCA2 6174delT frameshift mutation." (PMID 28055979, 2017). "BRCA1 and BRCA2 are two recognized tumor suppressor genes, for the encoded proteins play important roles in transcription and DNA repair of double-stranded breaks via homologous recombination." (PMID 28415599, 2017). "HRDetect identifies BRCA1/BRCA2-deficient tumours with 98.7% sensitivity (area under the curve: 0.98)." (PMID 28491135, 2017). "All pathogenic germline mutations in BRCA1 (n = 31) and BRCA2 (n = 16), known prior to smMIP‐based targeted sequencing, were called by the NextSeq software in 47 tumor samples derived from 38 patients." (PMID 27767231, 2017). "An intriguing observation is that BRCA2 mutations are more commonly found in tumor tissue exome sequencing but rarely in the plasma ctDNA mutation detection." (PMID 28472989, 2017). "This is consistent with the notion that BRCA2 is a key double strand DNA repair gene product and mutations of which render the tumor cells sensitive to DNA damaging chemotherapy and radiation treatment." (PMID 28472989, 2017).
tumor (continued). "Most tumours associated with germline BRCA1/BRCA2 loss of function mutations respond to DNA damaging agents, however, some do not." (PMID 28831036, 2017). "It remains to be shown if the temporal change in genomic stability of BRCA2-mutation carrier PCa tumours is relevant to other solid tumours with specific pre-dispositions for aggressive disease such as those arising in breast, colon and pancreas." (PMID 28067867, 2017). "Three different patient tumours were compared initially: two containing deleterious BRCA1 or BRCA2 mutations and one wild type status." (PMID 28211448, 2017). "All five tumor specimens with BRCA2 mutation had a reduced BRCA2 protein expression, however, a reduced BRCA2 protein expression was also detected in tumors harboring wildtype BRCA2 (63.6%)." (PMID 28676659, 2017). "We now show that USP21 interacts with and deubiquitinates BRCA2 and that USP21 loss results in decreased BRCA2 expression in tumor cell lines." (PMID 28743957, 2017). "Tumours arising in BRCA2 mutation carriers showed significantly higher methylation of candidate genes, than those arising in non-BRCA2 familial MBCs (average AMI 23.6 vs 16.6, p = 0.01, 45% of genes hypermethylated vs 34%, p < 0.01)." (PMID 28893223, 2017). "RHPS4 treatment elicited a marked delay in tumor regrowth (approximately 7 days in BRCA2-deficient compared to 4 days in BRCA2-proficient tumors)." (PMID 26748828, 2016). "As an important cofactor for BRCA2 in tumor suppression, BCCIP has been implicated in many important cellular processes with obvious links to cancer." (PMID 27535137, 2016). "We find two of the newly defined cisplatin-specific mutation types as causes of the reversion of BRCA2 mutations in emerging cisplatin-resistant tumours or cell clones." (PMID 27161042, 2016). "While PhenDC drastically reduced viability of Brca1−/− mouse tumor-derived cells, its toxicity against BRCA2-deficient V-C8 cells was rather modest." (PMID 26748828, 2016). "Although not yet formally demonstrated, an early role for BRCA2 in ICL repair would be consistent with the ICL sensitivity of BRCA2‐deficient cells and tumours." (PMID 27037238, 2016). "Only the BRCA2 deleted allele was retained in the ACC tumoral DNA compared with the control DNA suggesting a loss of heterozygosity in the tumor." (PMID 27603373, 2016). "Tumor cells carrying the mutations of the tumor suppressor genes BRCA1 or BRCA2 are defective in homologous recombination, and thus are sensitive to the inhibition of PARP activity, another key pathway involved in DNA repair." (PMID 26933818, 2016). "In a heterogeneous tumor population, BRCA2 inhibition will select for cells with deficient HRR while concomitant olaparib treatment will eliminate those cells." (PMID 26959114, 2016). "The expression of PARP1, γH2AX, BRCA1, and BRCA2 were significantly associated with each other and were associated with higher tumor stage and presence of distant metastasis." (PMID 27643881, 2016). "Although the mutation frequency observed is high, our sample size is relatively small and further studies are warranted to confirm the association of BRCA1/BRCA2 mutations with this rare neoplasia." (PMID 27532258, 2016). "Similar high tumor incidence has been reported in other mice carrying Brca2 hypomorphic alleles that result in viable mice, such as Brca2tm1Cam, Brca2Tr2014." (PMID 27490902, 2016). "Only the BRCA2 deleted allele was retained in the ACC tumoral DNA compared with the control DNA supporting a loss of heterozygosity in the tumor." (PMID 27603373, 2016). "An elegant study recently reported that loss of tumour suppressors BRCA1 or BRCA2 increases R-loop levels, because these proteins act to prevent R-loop formation." (PMID 27725641, 2016).
tumor (continued). "BRCA2 contained one promoter associated probe which also had large variation between the tumor-derived DNA samples, ranging from 4.49% to 41.88%." (PMID 27902704, 2016). "Two of 16 cases of this rare tumor (12.5%) were shown to have the BRCA2 Portuguese founder mutation, with a 14.3% (2/14) frequency observed when considering only the samples with mutations and those in which all BRCA1/BRCA2 coding regions were analyzed." (PMID 27532258, 2016). "Male BRCA2 mutation carriers more frequently have grade 2/3 vs. grade 1 tumours, compared with the large, unselected population of MBC cases from SEER." (PMID 26857456, 2016). "Predicted pathogenic germline mutations in BRCA1 and BRCA2 were identified in 1.36% and 1.64% of the cohort, respectively, and 2.22% of tumours harboured pathogenic CHEK2 germline mutations." (PMID 27161491, 2016). "Mutations in proteins essential for HR, such as the breast cancer early onset (BRCA1 & BRCA2) tumor suppressor genes, have been associated with increased risk of tumor development and enhanced sensitivity to chemotherapeutic agents." (PMID 28033382, 2016). "The BRCA2 mutated and wild type tumours showed similar radiation sensitivity, and treatment with olaparib did not further sensitize either model when compared to IR alone." (PMID 28033382, 2016). "BRCA1 and BRCA2 are mutated in 22% of tumours, owing to a combination of germline and somatic mutations." (PMID 27833130, 2016). "BRCA1 mutation-positive cases were found among the serous, endometrioid and mixed cell subtype adenocarcinomas in contrast to BRCA2 mutation carriers, which were exclusively found among the serous subtype tumours." (PMID 25884701, 2015). "One patient with a BRCA2-mutated tumor experienced complete remission of liver metastasis following cisplatinum chemotherapy." (PMID 25743105, 2015). "We systematically reviewed important differences in design between the studies and assessed their methodological rigor using a specially developed scoring-system aiming to give the best evidence regarding the prognosis of BRCA1- and BRCA2-associated tumours." (PMID 25816289, 2015). "Pathogenic alterations were reported in tumor as the predicted protein alterations, BRCA2 “R645fs*15′′ and MLH1 “E694*”." (PMID 25712765, 2015). "At the same time, highly heterogeneous short structural variants were discovered in PTEN, RB1, and BRCA2 in all tumor and CTC samples." (PMID 26575023, 2015). "Two pathogenic genomic alterations were reported from tumor testing, listed on the report as BRCA2 “R645Efs*15′′ and MLH1 “E694*”." (PMID 25712765, 2015). "Last, analysis of BRCA2 in CHLA-01-MED (second passage cells from the tumor at diagnosis) showed a BRCA2 6174delT frameshift mutation in one allele, similar to the BRCA2 6174delT germline mutation found in the germline of this patient and his mother." (PMID 26380221, 2015). "While we detected no BRCA mutations within the germlines of the patients analyzed in this study, the tumor tissues of two patients displayed somatic mutations in BRCA2 (Patient P2: frame shift DEL; Patient P5: missense mutation)." (PMID 26177635, 2015). "A FFPE tumour sample containing the BRCA2 c.10095delinsGAATTATATCT p.(Ser3366AsnfsTer4) variant was processed with a series of input DNA amounts from the recommended 80 ng down to 2.5 ng DNA input total (20 ng down to 0.6 ng DNA input per primer pool)." (PMID 25859162, 2015). "Combining radiation therapy with PARP inhibitors offers promise, since the inhibitors would lead to formation of double strand breaks from the single-strand breaks generated by the radiotherapy in tumor tissue with BRCA1/BRCA2 mutations." (PMID 25606064, 2015).